RAD51 (RAD51 recombinase)
Diseases named in the same sentence as RAD51 in open-access papers (continued):
Sharing a sentence is not in itself a finding about the gene and the disease.
cancer (continued). "By contrast, in cells lacking a BRCA2 carboxyl (C)-terminal region targeted by cancer-causing mutations, damage-induced RAD51 assemblies initiate but do not extend into filaments." (PMID 29309696, 2018). "New RAD51 mutants have been discovered from functional HR assays on tumor material, genome sequencing of patients with phenotypes like those of Fanconi anemia (FA) (a genetic disease including HR defects), and large-scale cancer genome sequencing." (PMID 30271574, 2018). "siRNA against RAD51 was functional and resulted in cell death of recipient cancer cells." (PMID 29541030, 2018). "RI-1, stably and irreversibly inhibits RAD51, sensitising cancer cells to MMC." (PMID 29757235, 2018). "Actually, tumor samples from patient P1052 carries two distinct variants one in MRE11A and one in RAD51, suggesting that also DSB repair may contribute to cancer development." (PMID 30283497, 2018). "Here, we focused on the human RAD51 paralogs—RAD51B, C, D, XRCC2, 3, and SWSAP1—and explored their known and emerging functions, the challenges in further uncovering their roles, and their association with cancer predisposition." (PMID 30551670, 2018). "Furthermore, our knowledge about RAD51 and the factors that modify its action can be exploited for cancer therapy." (PMID 31435521, 2018). "Additionally, it has been shown that RAD51 is overexpressed in a number of cancers (including sarcomas, breast, non-small cell lung, bladder, prostate and pancreatic)." (PMID 29757235, 2018). "This reduction was probably due to a decrease in RAD51 protein levels in response to treatment with the PI3K-inhibitor (data not shown) suggesting that PI3K inhibition directly impacts HR functionality in our studied cancer cells." (PMID 28886696, 2017). "Besides, our findings should elucidate how the 3′UTR variants regulate RAD51 activity and thus will pave the way to targeting of the RAD51 pathway as a cancer treatment." (PMID 27733989, 2016). "Indeed, in a HR-deficient background, Polθ becomes essential for cancer cells by promoting MMEJ and preventing toxic RAD51 structures." (PMID 27612511, 2016). "RAD51 levels have been shown to be higher in cancer cells as compared to normal cells." (PMID 27495836, 2016). "Furthermore, the inhibition of Rad51 promoted the resensitization of these previously resistant cells to anti-cancer therapy, which suggests that enhanced DNA repair activity in CSCs promotes their ability to overcome any double strand breaks during therapy." (PMID 27891292, 2016). "In addition, RAD51 small molecule inhibitors are currently being developed for cancer clinical trials." (PMID 27495836, 2016). "Taken together, the decreased level of RAD51 induced by oleandrin may contribute to the inhibition of HR pathway, and lead to the death of cancer cells." (PMID 27449097, 2016). "Our initial results showed that micromolar concentrations of vorinostat could lead to a major reduction in the level of BRCA1 and RAD51 and as expected vorinostat led to increased sensitivity of various cancer cell lines to ABT-888." (PMID 27196668, 2016). "In addition, RAD51 is intimately involved in both the pathogenesis of malignant tumors and progression of various types of cancer." (PMID 27733989, 2016). "Meanwhile, our data indicated that ubiquitin-ligating (E3) enzymes for Rad51 may be a potential target for cancer treatment." (PMID 26752698, 2016). "Our results also presented that oleandrin could reduce RAD51 expression and may inhibit HR pathway, this may increase the sensitivity of cancer cells to oleandrin." (PMID 27449097, 2016). "However, the expression level of RAD51 in oleandrin-treated cancer cells showed a significant reduction." (PMID 27449097, 2016).
cancer (continued). "Inhibitors against RAD51 could be used as therapeutic agents to treat cancer, either alone or in conjunction with DNA-damaging agents or ionising radiation." (PMID 27725183, 2016). "Importantly, our data indicate that a treatment schedule in which a short Plk1 inhibition using BI2536 is performed before IR reduces the formation of BRCA1 and Rad51 foci, leading to impaired HR repair and to radiosensitization of cancer cells." (PMID 26745677, 2016). "Additionally, inhibition of DNMT1 or elimination of Rad51 has been shown to sensitize cancer cells to chemotherapeutic agents." (PMID 27525019, 2016). "The accumulation of RAD51 on undamaged DNA has important implications for cancer etiology." (PMID 25765654, 2015). "The inhibition of Rad51 recombinase by curcumin is consistent with previous reports showing that curcumin decreases human RAD51 protein levels following treatment with DNA-damaging drugs in cancer cell lines." (PMID 26218133, 2015). "In addition, Rad51 is up-regulated in numerous cancers, especially high grade radioresistant tumors." (PMID 26599019, 2015). "Consequently, constitutive upregulation of RAD51 and HR in cancer cells has the potential to create resistance to DOX or other genotoxic drugs." (PMID 25401086, 2014). "Thus, inhibition of HOXA10 can downregulate EGR1, PTEN, and Rad51 paralogs in serial order to interfere with the HR system of cancer cells, making the cancer cell more vulnerable to temozolomide treatment." (PMID 25061500, 2014). "Indeed, siRNA strategies have been successfully used to enhance killing of cancer cells by cisplatin and attenuate RAD51-mediated radioresistance." (PMID 24971740, 2014). "Our group then pioneered the use of Rad51 promoter for cancer gene therapy." (PMID 24742710, 2014). "However, it remains to be elucidated if RAD51 overexpression in cancers is a consequence of activated DNA repair pathways, or a cause of genome instability." (PMID 25233079, 2014). "Conversely, Rad51 is also under-expressed in a number of cancer cells." (PMID 24795863, 2014). "Cancer cells may become resistant to cisplatin by increasing the activity of homologous recombination repair via Rad51 over expression." (PMID 24065387, 2014). "Downregulation of RAD51 by siRNA increases radio- or chemo-sensitivity of cancer cells." (PMID 24971740, 2014). "Rad51 is overexpressed in a wide variety of cancer cell types." (PMID 24742710, 2014). "We hypothesize that the observed delay in metastasis was due to poor seeding and growth of the RAD51 depleted cancer cells at secondary sites." (PMID 24811120, 2014). "However, too high or too low recombination activity appears to relate to cancer formation and cancer advancement, and the strand exchange activity of Rad51 is, therefore, tightly regulated in the cell." (PMID 24304898, 2014). "A high expression level of RAD51 observed in cancer cells could potentially put a stronger demand on B02 concentration to achieve cell sensitization to chemotherapeutic agents." (PMID 24971740, 2014). "However, a limiting factor in the use of Rad51 promoter is its relatively large size 6532bp required to achieve high expression in cancer cells." (PMID 24742710, 2014). "Thus, our current data provide evidence that specific RAD51 inhibitors can be instrumental for improving the efficacy of chemotherapies of cancer and development of novel combination cancer therapies." (PMID 24971740, 2014). "Here we show that a newly identified small molecule, IBR2, disrupts RAD51 multimerization, accelerates proteasome-mediated RAD51 protein degradation, reduces ionizing radiation-induced RAD51 foci formation, impairs HR, inhibits cancer cell growth and induces apoptosis." (PMID 23341130, 2013). "Thus, therapies targeting RAD51’s downregulation have been used to inhibit tumor growth and sensitize cancer cells to radio- and chemotherapies." (PMID 24367670, 2013).
cancer (continued). "Since then, additional several studies with a large sample size about RAD51 135G>C polymorphism with cancer risk have not been reported." (PMID 24040396, 2013). "Overexpression of RAD51 has been found in the majority of human tumor cells, and levels of RAD51 are positively correlated with the aggressiveness and increased invasiveness of cancers." (PMID 24367670, 2013). "One of these un-annotated genes, Bc055324, is a predicted protein coding gene, which has a high co-expression ratio of more than 0.7 with the cancer genes Rad51 and Ccdc6, indicating this gene is increased in expression in >70% of the cases when Rad51 is increased in expression." (PMID 23039964, 2012). "Abnormal expression of Rad51 has been reported in various malignant tumors." (PMID 26316936, 2012). "Nonetheless, Rad51 associates with chromatin during DNA replication in BRCA2-defective cells, and elevated expression of Rad51, which is often found in radioresistant cancer cells, bypasses the BRCA2 dependency of HR repair." (PMID 22325354, 2012). "Downregulation of RAD51 by RNA interference similarly radiosensitized the cancer cells, and, conversely, introduction of exogenous RAD51 was able to significantly counteract the radiosensitizing effect of berberine, thus establishing RAD51 as a key determinant in radiation sensitivity." (PMID 21858113, 2011). "Even though, no mutations of RAD51 have been found in cancers, its expression is elevated in many cancer cell lines; perhaps to provide an advantage to rapidly dividing cells by repairing DSBs that would lead to replication fork collapse." (PMID 21857994, 2011). "The use of Rad51 and Bax modulating compounds could offer women the opportunity to maintain fully functional germ cells despite cancer treatments or aging." (PMID 20169201, 2010). "RAD51 expression has also been found altered in both primary tumours and cancer cell lines." (PMID 16762046, 2006). "In contrast, there are reports of increased RAD51 expression in tumours and cancer cell lines." (PMID 16762046, 2006). "In contrast to the hMre11 and Rad51 data, the fraction of Rad50 foci-positive cells (filled symbols) in the irradiated cells from hypersensitive cancer patients (88%) was significantly higher (<0.005) than in control cells (41%) and cells from cancer patients with normal reaction to RT (44%)." (PMID 15150571, 2004). "The expression levels and focal nuclear distribution of DNA repair proteins, hMre11, Rad50 and Rad51 were investigated in skin fibroblasts strains derived from cancer patients with adverse early skin reaction to radiotherapy using Western blot and foci immunofluorescence techniques, respectively." (PMID 15150571, 2004). "The high expression of RAD51 in malignant cell clusters, along with its correlation with multiple aggressive phenotypes, suggests that it may promote tumour progression primarily by regulating malignant behaviours in cancer cells." (PMID 41350246, 2025). "Therefore, our results indicate that RAD51 expression is upregulated in the majority of cancers." (PMID 41350246, 2025). "In summary, targeting RAD51 or its pathways may improve cancer immunotherapy." (PMID 41350246, 2025). "By blocking RAD51, the whole process of telomere maintenance in cancers might be disrupted." (PMID 40723168, 2025). "Therefore, the circHIPK3/miR-107/RAD51 axis may be another mechanism that induces chemotherapy resistance in cancer." (PMID 40061896, 2025). "Importantly, ATR inhibition abolishes the restored RAD51 foci and the loading of RAD51 to replication forks in BRCA1-deficient, PARPi-resistant cancer cells, supporting the idea that ATR inhibition disrupts a common RAD51-mediated mechanism driving PARPi resistance." (PMID 39007266, 2024).
cancer (continued). "No cancer predisposition has been reported in the pathologies caused by RAD51 variants." (PMID 37190078, 2023). "Thus, EEPD1 (and RAD51) overexpression likely confers a selective advantage to cancer cells as they manage multiple types of stress, and it is also likely to confer resistance to replication stress-inducing cancer chemo- and radiotherapeutics." (PMID 38069223, 2023). "Our findings identified additional cellular processes that might be affected by cancer treatment strategies dependent on the stabilisation of RAD51 nucleoprotein filaments, namely the repair of DNA lesions, the restart of stalled replication forks, and the segregation of replicated DNA." (PMID 37239121, 2023). "This study hypothesized that although gene alterations of RAD51 might not be the major reason that drives cancers, the expression of RAD51 might associate with cancers." (PMID 35359409, 2022). "In addition, this study also analyzed the association of RAD51 and chemotherapy by plotting the expression of RAD51 in responder and nonresponder, chemotherapy predictive ROC plot, and chemotherapy response in RAD51 quartiles expression groups in four cancer types." (PMID 35359409, 2022). "However, it remains unknown if the alteration in resistance results in the survival association of RAD51, but the bioinformatics study in the general prognostic power of RAD51 in some cancer types have been reported." (PMID 35359409, 2022). "Interestingly, these cancer cells also show higher levels of RAD51 than hTERT-RPE cells." (PMID 35969531, 2022). "Thus, RAD51 might potentially be an exclusion biomarker for the inflammatory immune subtype in these cancer types." (PMID 35359409, 2022). "Therefore, to identify inhibitors of Rad51 is important to achieve effective treatment of cancers." (PMID 35220392, 2022). "Moreover, the treatment of cancer cells with chemotherapeutic drug (cisplatin) led to activation of mechanisms which disrupt immune surveillance and maintenance of genetic material, whereas addition of RAD51 inhibitor prevented activation of such mechanisms." (PMID 36428789, 2022). "This study proposed that the levels of RAD51 in some cancer types depended on proliferating T cells if there is a large proportion of T cells, but for most samples, T cells have a relatively low proportion and the major expression of RAD51 was from cancer cells." (PMID 35359409, 2022). "However, unlike other BRCA/FA genes, RAD51—the central recombinase of the HR pathway—is not commonly mutated in cancer." (PMID 33709473, 2021). "Since RAD51 is often overexpressed in cancer cells and that this overexpression correlates with poor patient survival, we suggested that B02-iso analogs may have a more substantial antiproliferative effect on cancer cells than on normal cells." (PMID 34208492, 2021). "Importantly, CMM patients bearing RAD51 mutations (but no mutations of other HR genes) do not exhibit cancer predisposition." (PMID 34316706, 2021). "Thus, elevated levels of RAD51 expression could act as a safeguard to avoid massive fork collapse and protect cancer cells from the accumulation of DNA breaks." (PMID 34208195, 2021). "Furthermore, cancer therapeutics can affect the expression of RAD51, indicating that using paired pre- and posttreatment samples could add the predictive value of RAD51." (PMID 33952262, 2021). "Moreover, it was shown that the survival of cancer patients expressing higher levels of RAD51 is shorter and that a reduced amount of RAD51 in the cellular model, following antisense or ribozyme treatment, increases the effectiveness of cancer treatment by radiotherapy." (PMID 34576930, 2021). "Thus far, RAD51 is regarded as a desirable target in cancer therapy." (PMID 34782617, 2021).
cancer (continued). "This overexpression is associated with poor prognosis as a consequence of increased ability to repair lesions induced by DNA-damaging therapeutic agents; cancer cells overexpressing RAD51 could be selected during tumour progression because of this survival advantage." (PMID 34316706, 2021). "Thus, our findings uncovered the novel mechanism of bidirectional effect of VPA under IR treatment both in vitro and in vivo, VPA can directly target RFWD3 and then trigger Rad51 ubiquitination during cancer radiotherapy and limit radiotoxicity on normal cells." (PMID 33842359, 2021). "However, it is not yet fully clear whether the CHD4/p300 interaction is critical for RAD51 upregulation or whether it may play a role in the resistance of cancer cells to DNA-damaging treatment." (PMID 34208195, 2021). "However, genetic and pharmacological inhibition of RAD51 further sensitized BL0479-72 cells to TMZ + VE821 compared to control cells, in line with the notion that HR deficiencies increase reliance on ATR activity in cancer cells." (PMID 34676045, 2021). "The proportion of Rad51 + cells was significantly higher in the CD44high/CD166high population than in the CD44low/CD166low population in all groups with and without irradiation at any dose, thus, indicating the increased activity of the HR system in cancer stem-like cells." (PMID 33673439, 2021). "Therefore, rather than protecting against genomic instability, RAD51-mediated fork reversal can trigger mutagenic replication in BRCA-deficient cancer cells, suggesting that the reversed fork is an inherently vulnerable DNA structure." (PMID 32938550, 2021). "Therefore, further studies on RAD51 expression in a variety of cancers are necessary." (PMID 31973027, 2020). "The impaired ability to form RAD51 foci after DNA damage may identify cancers with defective HR20." (PMID 32471999, 2020). "Thus, it is reasonable to propose that any small molecule that may alter the dynamics of the Rad51-Hsp90 interaction is likely to impact DSB repair in cancer cells." (PMID 30894431, 2019). "It has been proposed that this upregulation of RAD51 may be a result of the high proliferative index of tumour cells, and it has been shown that lowering RAD51 expression or activity (through inhibition) can sensitise cancer cells to chemotherapeutics (such as cisplatin, doxorubicin or IR)." (PMID 29757235, 2018). "However, we propose that abnormally high expression of resection components and Rad51 might be a driving force for genome instability and cancer formation in old organisms and future studies will directly test this possibility." (PMID 28000382, 2017). "It is known that PALB2 cancer-related missense variants L393W, T1030I and L1143P in the WD40 domain could interfere with PALB2 association with RAD51 and BRCA2, prompting carriers to be defective in DNA damage repair by HR, leading to an increased sensitivity to IR-treatment." (PMID 28858227, 2017). "RAD51 genetic variations may contribute to the development of cancers." (PMID 27733989, 2016). "In conclusion, oleandrin could effectively induce the death of cancer cells at a very low concentration; the anti-tumor role of oleandrin may be related with DNA damage repair; and oleandrin may be a novel HR inhibitor by suppressing the expression of Rad51." (PMID 27449097, 2016). "Moreover, IBR2 effectively inhibits the proliferation of CD34+ progenitor cells from CML patients, suggesting that small molecule inhibitors of RAD51 may provide a novel class of broad-spectrum therapeutics for difficult-to-treat cancers." (PMID 25749979, 2015). "Therefore the problem of genetic variability of the RAD51 gene in cancer is worthy studying." (PMID 25743260, 2015). "Moreover, Rad51 was reported to have increased activity in cancer cells compared to normal cells." (PMID 26397223, 2015).